CTLA4 (cytotoxic T-lymphocyte associated protein 4)
Diseases named in the same sentence as CTLA4 in open-access papers (continued):
Sharing a sentence is not in itself a finding about the gene and the disease.
uveal melanoma (21 papers, 2018 to 2025). A melanoma derived from melanocytes of the uveal tract. "Further clinical trials are needed to establish the role of CTLA-4 and PD-1 inhibition for the adjuvant treatment of high-risk uveal melanoma." (PMID 30699934, 2019). "Grynberg S included 38 patients with metastatic uveal melanoma in the study; 50% of patients received anti-PD-1 therapy and 50% received combined anti-PD-1 and anti-CTLA-4 therapy." (PMID 40406270, 2025). "For instance, tumor-infiltrating lymphocytes have been observed in uveal melanoma, with immune checkpoint molecules such as PD-1 and CTLA-4 facilitating immune evasion." (PMID 41268982, 2025). "Within the cohort of uveal melanoma, a case-by-case analysis of four patients revealed a poor response to immunotherapy, consistent with previous studies, showing low efficacy of anti-PD-1 and anti-CTLA-4 therapies in uveal melanoma." (PMID 38903495, 2024). "Epigenetic changes downregulating PD-L1 and other key immune checkpoints, including LAG-3 and CTLA-4, have been observed in uveal melanoma with BAP1 disruption." (PMID 36674809, 2023). "With recent advancements in CTLA-4 inhibition, PD-1 inhibition, and combined checkpoint blockade, immunotherapy is a promising avenue of treatment in uveal melanoma." (PMID 30699934, 2019). "As a caveat, however, CTLA-4 inhibitors as single-agent therapy in recent phase 2 studies of metastatic uveal melanoma have shown an equally unimpressive 0% ORR, with significant grade 3–4 toxicities in approximately 35% of cases." (PMID 30699934, 2019). "The objective was to assess the response rate and survival of patients with metastatic mucosal melanoma (MM) and uveal melanoma (UM) treated with anti-CTLA-4 or anti-PD-1 monoclonal antibodies (mAbs)." (PMID 30631354, 2018). "ICIs, including anti-CTLA-4 and anti-PD-1 agents, aim to overcome this evasion by reinvigorating exhausted T cells and have shown improved survival in metastatic uveal melanoma patients, albeit with notable immune-related adverse events such as non-infectious uveitis." (PMID 41268982, 2025). "As previously discussed, the expression of additional immune checkpoint receptors such as LAG-3 or distinct expression levels of these immune checkpoints could also explain the unfavorable response rates to anti-CTLA-4 and anti-PD-1 therapies in uveal melanoma." (PMID 37004702, 2023). "While response rates are low for CTLA4 and PD-L1 immune checkpoint inhibition in metastatic uveal melanoma, other immune checkpoints are at play and increasing the T- and NK- cell response in the metastatic niche may inhibit both survival and growth of uveal melanoma micrometastases." (PMID 35413810, 2022). "Immune checkpoint inhibitors targeting CTLA-4 and the PD-1/PDL-1 axis have demonstrated antitumor activity in uveal melanoma." (PMID 36674809, 2023). "CTLA-4 blockade with ipilimumab improved two-year survival in metastatic uveal melanoma (34% vs. 12% with chemotherapy), but 18% developed non-infectious uveitis requiring steroid-sparing agents like mycophenolate." (PMID 41268982, 2025). "Similarly, in uveal melanoma (UVM) and liver hepatocellular carcinoma (LIHC), CRABP2 expression is significantly correlated with seven of these immune checkpoint genes (LAG3, CTLA4, PDCD1LG2, HAVCR2, PDCD1, CD274, and TIGIT)." (PMID 39991584, 2025). "In addition, novel CTLA4-free combinations such as Relatlimab, a human IgG4 LAG-3-blocking antibody in combination with nivolumab may also play a role in uveal melanoma treatment in the future." (PMID 34298857, 2021). "Thus, to optimize the uveal melanoma therapy and obtain greater efficacy in the future, studies could be conducted with darovasertib, in combination with other drugs that inhibit other tyrosine kinases, such as VEGF-B and PD-1/CTLA-4 inhibitors." (PMID 37576814, 2023).
uveal melanoma (continued). "Unfortunately, patients with uveal melanoma do not receive benefit from anti-PD1 or anti-CTLA4 therapy, and the reasons behind poor ICI immunotherapy response in uveal melanoma are unclear." (PMID 36248850, 2022).
Allergy (20 papers, 2011 to 2026). An allergy is an immune response or reaction to substances that are usually not harmful. "The spy-VLP vaccines also effectively broke B cell self-tolerance and induced potent and durable antibody responses upon vaccination with cancer or allergy-associated self-antigens (PD-L1, CTLA-4 and IL-5)." (PMID 27117585, 2016). "Compared with steady state, both tolerance and allergy conditions suppressed Ctla4 and upregulated Ikzf2." (PMID 37191720, 2023). "It has been shown that the circulating form of CTLA-4 is elevated in patients with hymenoptera allergy and can be down regulated by immunotherapy." (PMID 22723841, 2012). "Ohnmachtet al. proposed that RoR-γt iTreg cells may regulate allergic diseases by restraining TH2 cell-mediated responses in the gut by a CTLA-4-dependent mechanism." (PMID 29375821, 2018). "In such allergic disease, S. mansoni antigens downmodulate the Th2 exacerbated inflammatory response in vitro by inducing the production of IL-10 and the expression of the regulatory molecules, CTLA-4 in T lymphocytes." (PMID 23209879, 2012). "The types of TAARs included in the present study were allergic reaction and FNHTR, so these significant CTLA4 SNPs would explain the situation that these adverse reactions occur even when transfusing leukoreduced blood components." (PMID 31766247, 2019). "The multiple linear regression analysis showed that after Derp 1 specific stimulation, allergy (R + AR) correlated positively with percentages of ICOS, IL-13 and IL-4-expressing T cells and negatively with CTLA-4 and IL-10-expressing T cells." (PMID 21356099, 2011). "After subdivision of these three basic groups according to the children’s allergy status at the age of 10 years, no significantly different cell surface presence of CTLA-4 was detected in the children of healthy mothers." (PMID 36703968, 2022). "Control of maternal atopy in pregnancy and modulation of gene expression such as CTLA4 and IL13 may be a target for decreasing antenatal IgE production and possibly lowering perinatal allergy sensitization." (PMID 22481967, 2012). "At the age of 18 months, the expression of FOXP3, GATA-3, and CTLA-4 in Tregs was higher in the children with allergen-specific IgE sensitization without signs of clinical allergy when compared to the children who did not develop clinical allergies." (PMID 31749800, 2019).
brain tumors (20 papers, 2016 to 2025). "In recent years, drugs targeting the cytotoxic T lymphocyte-associated protein 4 (CTLA-4) or programmed cell death protein 1 (PD-1) pathways have also investigated in the context of primary and secondary brain tumors." (PMID 34203062, 2021). "Additionally, the upregulation of immune checkpoint molecules such as PD-L1 and cytotoxic T lymphocyte-associated protein 4 (CTLA4) in the brain tumor microenvironment may facilitate immune evasion and metastasis." (PMID 40149281, 2025). "The crucial checkpoints in pediatric brain tumors are cytotoxic T lymphocyte antigen-4 (CTLA-4), programmed cell death protein-1 (PD-1) and programmed death-ligand 1 (PD-L1), OX-2 membrane glycoprotein (CD200), and indoleamine 2,3-dioxygenase (IDO)." (PMID 37605389, 2024). "Cancer immunotherapy targeting immune checkpoints (IC) (PD-1, PD-L1, and CTLA4) has been getting disappointing outcomes in brain tumors." (PMID 36825029, 2023). "On the other hand, recent studies focus on new approaches to increase the efficacy of PD-1/PD-L1 and CTLA4 inhibitors in brain tumours." (PMID 33670244, 2021). "Consistently, we found that specific pharmacochemical ablation of dorsal MLVs significantly blocked DC trafficking from brain tumors to dCLNs, and reduced the efficacy of anti-PD-1/CTLA-4 combination therapy." (PMID 32094452, 2020). "Although baseline tumor-immune microenvironments were similar at brain and extracranial tumor sites, response to ISV+α-CTLA-4 was divergent with reduced infiltration and activation of immune cells in brain tumors." (PMID 32690669, 2020). "Like results from IHC and flow cytometry, we observed a general pattern of decreased production of immune stimulatory cytokines in the brain tumor microenvironments compared with extracranial tumor microenvironments in ISV + α-CTLA-4 treated mice." (PMID 32690669, 2020). "ISV + α-CTLA-4 significantly increased survival of mice bearing B78 brain tumors compared with untreated mice (p<0.05, n=10), but the addition of ISV to α-CTLA-4 did not significantly improve survival compared with α-CTLA-4 alone." (PMID 32690669, 2020). "Following ISV+α-CTLA-4, production of immune-stimulatory cytokines was greater in left flank compared with brain tumor grafts." (PMID 32690669, 2020). "We performed IHC using innate immune lineage markers of myeloid cells and monocytes/macrophages on brain tumors from untreated mice compared with ISV + α-CTLA-4 treated mice." (PMID 32690669, 2020). "DC trafficking into CLNs was impaired when dorsal MLVs were interrupted, therefore we predicted that the anti-PD-1/CTLA-4 combination treatment against brain tumors would have poor effects in MLV-defective mice." (PMID 32094452, 2020). "Inhibition of the PD-1/PD-L1 and CTLA-4 immune checkpoints is a promising therapeutic approach for the treatment of primary brain tumors." (PMID 29396294, 2018). "A third dominant and critical immunosuppressive pathway relevant to brain tumors is mediated by CTLA-4, which simultaneously inhibits effector T cell activation/proliferation and Treg activation/function in GBM." (PMID 27057463, 2016). "Additionally, we observed administration of α-CTLA-4 after radiation decreases brain tumor burden compared to α-CTLA-4 alone and administration of α-CTLA-4 prior to radiation." (PMID 38240876, 2024). "The expression of several checkpoints in brain tumours, including programmed cell death protein 1 (PD-1) and cytotoxic T-lymphocyte-associated protein 4 (CTLA-4), is comparable to that observed in non-CNS origin malignancies." (PMID 33670244, 2021). "Blocking CTLA-4 enhances tumor immunity in mouse models of brain tumor." (PMID 31142380, 2019). "This makes CTLA-4 inhibitors promising antitumor agents, since CTLA-4 is involved in cancer development, including brain tumors." (PMID 40895574, 2025). "Among ISV + α-CTLA-4 treated mice, left flank tumors showed increased CD8+ infiltration and CD8+:FOXP3+ ratio compared with brain tumors." (PMID 32690669, 2020).
brain tumors (continued). "ISV+α-CTLA-4 increased CD8+ and CD4+ T cells in flank and brain tumors compared with untreated mice." (PMID 32690669, 2020). "In high grade brain tumors, Tregs suppress activation, proliferation and cytokine production of CD4+/CD8+ T cells via secreted cytokines such as TGF-B and IL-10 or via cell-to cell contact mediated by the constitutively expressed CTLA-4 and PD-L1 checkpoints." (PMID 30974896, 2019). "Our data indicate that combining D2C7-IT with antibodies that block the immune checkpoints PD-1 (to reactivate exhausted tumor-specific T cells) and CTLA-4 (to inhibit immunosuppressive Tregs), or PD-L1 (to block PD1/PDL1 pathway) may reinstate immunosurveillance in brain tumors." (PMID 31142380, 2019). "Thus, it will be interesting to determine whether co-inhibiting CTLA-4 and IDO1 lacks an additive/synergistic impact against brain tumors or if other undiscovered immunosuppressive mechanisms remain independent of the interaction." (PMID 27057463, 2016). "More recent research has demonstrated that immunotherapy options, such as Programmed Cell Death Protein-1 (PD-1) or Cytotoxic T-Lymphocyte Associated Protein 4 (CTLA-4) inhibition, may prove useful for treating brain tumors, but these have not yet succeeded in phase 3 clinical trials." (PMID 34077449, 2021).
metastatic colorectal cancer (19 papers, 2018 to 2025). "Ipilimumab and tremelimumab, which are CTLA4 inhibitors, were effective for improving the survival of patients with metastatic colorectal cancer in phase II clinical trials." (PMID 36910014, 2023). "ICIs against programmed death-1 (PD-1) and cytotoxic T lymphocyte antigen-4 (CTLA-4) proteins were highly effective in advanced dMMR metastatic colorectal cancer, especially combination therapy provided improved efficacy relative to anti-PD-1 monotherapy." (PMID 34642306, 2021). "Furthermore, dual-agent approaches combining PD-1 and cytotoxic T lymphocyte-associated antigen 4 (CTLA-4) inhibitors show potential, as seen in CheckMate-142, which reported a 55% ORR in dMMR/MSI metastatic colorectal cancer." (PMID 40292281, 2025). "Indeed, preclinical studies using targeting innate immune cells in mouse models, suggest novel therapeutic strategies through inhibiting immunosuppressive MФs, activating ILC3s and DCs, either alone or in combination with anti-PD-1/anti-CTLA-4 therapy in primary or metastatic colorectal cancer." (PMID 36189323, 2022). "The immune checkpoint inhibitor, nivolumab, either alone or in combination with the CTLA-4 inhibitor ipilimumab, has also been previously approved in patients with MSI metastatic colorectal cancer who have been previously treated with systemic therapies." (PMID 37239414, 2023). "Immunotherapy of immune checkpoint inhibition targeting PD1 and CTLA-4 proteins has been shown to be effective in dMMR-MSI-H tumors and has become the standard of care for patients with metastatic colorectal cancer." (PMID 36232851, 2022). "However, the clinical relevance of CTLA-4 inhibition in addition to PD-1/PD-L1 inhibition remains to be demonstrated, especially in light of the limited efficacy of durvalumab and tremelimumab in MSS metastatic colorectal cancer." (PMID 34369992, 2021).
antibody deficiency (18 papers, 2017 to 2024). "Our study indicated that the onset of AD was more frequent before that of hypogammaglobulinemia in IKAROS deficiency and after hypogammaglobulinemia onset in CTLA4 deficiency." (PMID 35087518, 2021). "Alternatively, the number of remission of AD per 1 person-year, which is the sum of the patient AD duration, was highest in IKAROS deficiency before the onset of hypogammaglobulinemia, whereas remission was achieved in a few patients with CTLA4 deficiency." (PMID 35087518, 2021). "We performed systematic literature reviews of IKAROS and CTLA4 deficiencies and revealed a possibility that the onset of AD was earlier than that of hypogammaglobulinemia in IKAROS deficiency." (PMID 35087518, 2021). "The onset of AD per 1 person-year, which is the sum of the patient follow-up duration, was highest in CTLA4 deficiency after the onset of hypogammaglobulinemia." (PMID 35087518, 2021). "CTLA4 haploinsufficiency, caused by LOF mutations in CTLA4, was first described in 2014 in families with AD inherited form of immune dysregulation, characterized by hypogammaglobulinemia, infectious susceptibility and auto-immunity." (PMID 34867986, 2021). "Our data revealed that the patient’s hypogammaglobulinemia is associated with CTLA-4 haploinsufficiency, increased JAK3 activity, and increased percentages of circulating CD4+ and CD8+ effector memory T cells." (PMID 29375547, 2017). "Analyzing the exomes of a primary antibody deficiency cohort of 37 individuals from 9 families, we identified in one family a novel heterozygous missense mutation (p.Y139C) in the CTLA4 gene." (PMID 29375547, 2017). "Furthermore, CD4cyt were highly expanded in blood samples from CTLA4+/− patients, in whom hypogammaglobulinemia and deficiencies of total B cells or B-cell subsets were common." (PMID 37161048, 2023). "Furthermore, we conducted a retrospective longitudinal study on IKAROS and CTLA4 deficiencies in our Japanese cohort and determined a different onset order of hypogammaglobulinemia and AD in the two conditions." (PMID 35087518, 2021). "In some patients, CD21low B cells, which are said to be exhausted, have been observed to be expanded in patients with CTLA4 deficiency, and this population has been simultaneously used to explain the hypogammaglobulinemia, and the increased incidence of autoantibodies." (PMID 35154081, 2021). "Furthermore, our observation of the amelioration of hypogammaglobulinemia after abatacept treatment in patient 15.1 suggests a direct role of activated T cells in the hypogammaglobulinemia associated with CTLA4 deficiency." (PMID 35087518, 2021). "However, patients with CTLA4 deficiency are more likely to develop AD with increasing age than with developing hypogammaglobulinemia." (PMID 35087518, 2021). "Furthermore, patients with heterozygous mutations in CTLA4 also often exhibit B-cell defects and hypogammaglobulinemia, and the reason for this remains unclear." (PMID 37161048, 2023). "For instance, mutations in TNFRSF13B, NFKB1, NFKB2, CTLA4 and STAT3 are indications for the early molecular diagnosis of patients with predominantly antibody deficiency such as predominantly antibody deficiencies." (PMID 37033178, 2023). "A number of previous studies have outlined the clinical phenotypes of large patient groups with antibody deficiency who have mutations in selected genes, including the TACI gene, CTLA4, NFKB1, NFKB2, STAT3, PI3KCD, or LRBA." (PMID 38274105, 2023). "Hypogammaglobulinemia and AD were identified in 9 (60%) and 7 (47%) patients with IKAROS deficiency, and 15 (48%) and 24 (77%) patients with CTLA4 deficiency." (PMID 35087518, 2021). "Among the 9 and 15 patients with hypogammaglobulinemia in IKAROS and CTLA4 deficiency conditions, respectively, only one patient with CTLA4 deficiency (patient 15.1) achieved remission." (PMID 35087518, 2021).
antibody deficiency (continued). "The cumulative incidences of hypogammaglobulinemia and AD are 67%-86% and 3%-33% in IKAROS deficiency and 20%-71% and 61%-86% in CTLA4 deficiency, respectively." (PMID 35087518, 2021). "CTLA4 heterozygous mutation was first described as a cause of CVID-like syndrome that displayed a significant overlap with CVID phenotype, including hypogammaglobulinemia, low B cell counts and immune dysregulation with variable organ involvement." (PMID 30723478, 2018). "CTLA4+/− patients exhibit defects in B cells and hypogammaglobulinemia, and the reason for these characteristics remains unclear." (PMID 37161048, 2023). "Patients with CTLA-4 haploinsufficiency patients frequently fulfill diagnostic criteria for common variable immunodeficiency (CVID) due to a marked decrease in switched memory B cells and hypogammaglobulinemia (IgA, IgG, and/or IgM)." (PMID 37702894, 2023). "These systematic literature reviews suggest that patients with IKAROS deficiency develop in the order of AD and hypogammaglobulinemia, whereas those with CTLA4 deficiency do not." (PMID 35087518, 2021). "While antibody deficiency has been observed in humans with LRBA deficiency, and this might reinforce the evidence that CTLA4 deficiency causes antibody deficiency, other potential mechanisms, most notably B cell intrinsic defects in autophagy could explain this phenotype." (PMID 35154081, 2021). "Furthermore, AD remission was more frequent before the onset of hypogammaglobulinemia in IKAROS deficiency but not in CTLA4 deficiency." (PMID 35087518, 2021). "After a comprehensive work-up and worsening hypogammaglobulinemia over time, the patient was diagnosed with PAD, while the final diagnosis of a CTLA4 defect and the immune dysregulating syndrome were made postmortem." (PMID 38792965, 2024).